ALDOA (aldolase, fructose-bisphosphate A)
Diseases named in the same sentence as ALDOA in open-access papers (continued):
Sharing a sentence is not in itself a finding about the gene and the disease.
hepatocellular carcinoma (25 papers, 2011 to 2025). A malignant tumor that arises from hepatocytes. "High expression of ALDOA is associated with poor prognosis in hepatocellular carcinoma." (PMID 37090703, 2023). "In addition to metabolic regulation, ALDOA has been implicated in immune modulation, with emerging evidence suggesting that its expression correlates with immune cell infiltration patterns in tumors such as hepatocellular carcinoma." (PMID 41239433, 2025). "For example, in hepatocellular carcinoma, targeting ALDOA has been shown to disrupt glycolytic balance and induce energy stress due to the accumulation of fructose-1,6-bisphosphate (FBP), thereby impairing tumor cell survival." (PMID 41239433, 2025). "Elevated ALDOA expression has been reported in hepatocellular carcinoma, breast cancer, colorectal cancer, and lung cancer, where it promotes tumor cell proliferation, migration, and invasion." (PMID 41239433, 2025). "Targeting glycolysis by disrupting the catalytic activity of ALDOA led to severe energy stress and cell cycle arrest in murine and human hepatocellular carcinoma cell lines." (PMID 39833612, 2025). "ALDOA, an oncogene, has been identified as being involved in tumor cell malignant growth and worsening prognosis in hepatoma and pancreatic cancer." (PMID 37091782, 2023). "This study shows that high expression of ALDOA contributes to the development and poor prognosis of hepatocellular carcinoma and will be a target and potential prognostic biomarker for the treatment of HCC." (PMID 36494481, 2022). "Mechanistic studies suggest that ALDOA is a direct target of miR-34a-5p, which can inhibit glycolysis in hepatocellular carcinoma cells by targeting the 3′UTR of ALDOA." (PMID 36494481, 2022). "In this study, we investigated the expression pattern of ALDOA in hepatocellular carcinoma (HCC) and its biological role in tumour progression." (PMID 36494481, 2022). "It is worth noting that ALDOA is highly expressed in various cancers, such as colorectal cancer, hepatocellular carcinomas, and pancreatic cancer." (PMID 35096824, 2021). "Previous bioinformatics results also indicated that ALDOA expression was correlated with prognosis in bladder cancer, hepatocellular cancer." (PMID 34925439, 2021). "Key metabolism enzyme Aldolase A (ALDOA) has been shown to be highly expressed and involved in various kinds of cancers including hepatocellular carcinoma." (PMID 33994862, 2021). "Previous studies reported that upregulation of ALDOA is correlated with poor prognosis in colorectal cancer, gastric cancer, and hepatocellular carcinoma." (PMID 34925439, 2021). "Although ALDOA is an important oncogene in several cancer types, including non-small cell lung cancer, pancreatic cancer and hepatocellular carcinoma, it is a tumor suppressor in others, including prostate adenocarcinoma and stomach adenocarcinoma." (PMID 34869733, 2021). "Literature data shows that ALDOA is over-expressed in many types of cancers, including hepatocellular carcinoma, squamous cell lung cancer, osteosarcoma, colorectal cancer." (PMID 28686225, 2017). "Experimentally validated data reveal that miR-122 suppresses tumors and targets ALDOA in hepatocellular carcinoma." (PMID 26590260, 2016). "Overexpression of ALDOA is observed in various cancers including lung, renal cell and hepatocellular carcinoma, suggesting enhanced glycolysis in these cancer cells." (PMID 24465716, 2014). "Moreover, we found that depletion of ALDOA extended survival and reduced cancer cell proliferation in an animal model of hepatocellular carcinoma." (PMID 39833612, 2025). "Furthermore, downregulation of ALDOA induces pyrimidine deprivation and cell cycle arrest in cancer cells and reduced tumour growth in a mouse model of hepatocellular carcinoma (HCC)." (PMID 39833612, 2025).
hepatocellular carcinoma (continued). "Additionally, in previous studies, positive effect of ALDOA on initialization and progression of other cancers, such as colorectal cancer, oral tumor, osteosarcoma and hepatocellular carcinoma, had also been demonstrated." (PMID 28191039, 2017). "Nonetheless, it should be noted that ALDOB was found to be down-regulated in the progressive stages of hepatocellular carcinoma, probably due to transition of the cancerous cells into utilizing alternative paths for energy sources, for instance – ALDOA overexpression." (PMID 24993527, 2014). "Notably, ALDOA has been found highly expressed in a variety of malignant cancers, including human lung squamous, renal cell and hepatocellular carcinomas." (PMID 24465716, 2014). "Notably, ALDOA is highly expressed in a variety of malignant cancers, including renal cancer, human lung squamous cell carcinoma, and hepatocellular carcinomas, suggesting it could promote cancer growth by enhancing glycolysis." (PMID 27936075, 2016). "At the same time, FTO demethylates ALDOA transcripts, stabilizing them and promoting their persistence, ultimately leading to the metabolic adaptation of cancer cells to hypoxia, enhancing glycolysis and hepatocellular carcinoma (HCC) progression." (PMID 40102715, 2025). "For instance, the change in miR-122–5p and ALDOA reveals the negative correlation significantly only in human hepatocellular carcinoma (P-value = 3.9e−7 and R = −0.639)." (PMID 26590260, 2016). "Only hepatocellular carcinoma exhibits a significantly negative correlation between miR-122–5p and ALDOA (P-value = 3.9e−7 and R = −0.639)." (PMID 26590260, 2016).
breast carcinoma (22 papers, 2012 to 2025). "Among the genes of the five proteins selected, GPI, LDHA, TPI1, and ALDOA showed high expression in both breast cancer and colorectal cancer and were associated with poor patient prognosis." (PMID 38419074, 2024). "Targeting ALDOA in this context has been shown to significantly improve survival rates in breast cancer models." (PMID 40520908, 2025). "ALDOA, a pivotal glycolytic enzyme, has been identified as an extracellular tumor suppressor protein in breast cancer." (PMID 38389836, 2024). "More importantly, glycolysis enzymes (GPI, LDHA, TPI1, and ALDOA) were significantly enriched in the exosomes of primary tumors of both canine mammary tumor and human colorectal tumor, compared to metastases." (PMID 38419074, 2024). "The results showed that ALDOA was highly expressed in bladder cancer, breast cancer, kidney cancer, liver cancer, lymphoma, myeloma, and pancreatic cancer, and low in brain and central nervous system (CNS) cancer, esophageal cancer, and leukemia." (PMID 35804089, 2022). "According to our result, the expression level of ALDOA was significantly related to the prognosis of brain cancer, skin cancer, lung adenocarcinoma and breast cancer in the PrognoScan database." (PMID 35804089, 2022). "Further, knocking down ALDOA blocked breast cancer cells in the G0/G1 phase under minimized glycolysis." (PMID 28191039, 2017). "Spatial transcriptomic data of CD68, a macrophage marker, was used to confirm this relationship, showing co-expression of ALDOA and CD68 in macrophages within both breast cancer and melanoma samples." (PMID 41239433, 2025). "ACTG, ENOA, BIP, ALDOA, TBB5 and lncRNA TPA mRNA expression levels in breast cancer tissues (−χ ̄ ± s, n = 3)." (PMID 34422811, 2021). "Interestingly, we observed that one set of proteins was identified more frequently, with HLA-A, HLA-B, A2M, ACTB, ALDOA, ANXA2, and FN1 identified in at least 13 of 22 studies that explored the vesicular proteome in breast cancer." (PMID 37629204, 2023). "Interestingly, both ALDOA and SLC16A3 are also suggested to be hypoxia responsive and is upregulated in hypoxic breast cancer with poor outcome." (PMID 23216862, 2012). "Though there were no specific studies demonstrating the relationship between ALDOA/PFKL/PGK1 and TNBC, a previous study reported that aerobic glycolysis is crucial for modulating breast cancer cell proliferation, invasion, migration, and metastasis both in vitro and in vivo." (PMID 34490098, 2021). "Using transcriptome sequencing data of the CSC subpopulation in SUM149 human breast cancer cell line from GSE132083, we compared the glycolytic gene expression profiles between the CSC group and non-CSC group, and found that SLC2A1, HK2, ALDOA, ENO1, LDHA and PDK1 were upregulated in the CSC group." (PMID 34052833, 2021).
pancreatic cancer (22 papers, 2019 to 2025). "Previously, studies have shown that ALDOA was highly expressed in colon cancer, pancreatic cancer and osteosarcoma, and was associated with their poor prognosis." (PMID 33941139, 2021). "ALDOA, the gene encoding the glycolysis enzyme that converts fructose-1,6-bisphosphate to glyceraldehyde-3-phosphate, has been shown to correlate with poor prognosis in pancreatic cancer patients." (PMID 31861288, 2019). "The poor prognosis of pancreatic cancer predicted by ALDOA is partly because of its regulation of E-cadherin expression." (PMID 36030248, 2022). "In pancreatic cancer and bladder cancer cells, ALDOA-silencing increases E-Cadherin and decreases N-Cadherin expression." (PMID 35222014, 2021). "Aldolase A (ALDOA), a key glycolytic enzyme has been reported to be highly expressed in several cancers including pancreatic cancer, clear cell renal carcinoma, cervical, gastric cancer and most recently in HCC." (PMID 33865438, 2021). "Overexpression of human ALDOA in pancreatic cancer cells results both in increased rates of glycolysis and increased metastasis, leading to poor prognosis and reduced survival rates." (PMID 34458323, 2021). "Our previous results showed that ALDOA promoted proliferation and metastasis in pancreatic cancer cells." (PMID 34565365, 2021). "In our research, we probed the potential role of ALDOA in the cell cycle arrest induced by DNA damage in pancreatic tumour cells and discovered that ALDOA participated in regulating the DDR and attenuated the cell cycle arrest induced by DNA damage." (PMID 34565365, 2021). "Our previous study revealed that ALDOA, an oncogene, can promote the proliferation and metastasis of pancreatic tumours." (PMID 34565365, 2021). "ALDOA is a glycolytic enzyme found mainly in developing embryos, adult muscle and various malignant tumours, including pancreatic tumours." (PMID 34565365, 2021). "Supportive of this role of ALDOA are other studies showing that silencing of ALDOA increased E-cadherin (epithelial marker) and decreased N-cadherin (mesenchymal marker) in pancreatic cancer and bladder cancer cell lines." (PMID 32318352, 2020). "The function of ALDOA in pancreatic cancer could be attributed to its regulatory role of HIF1α and c-Myc." (PMID 39755705, 2025). "ALDOA increased most markedly in response to TGF-β and further the results of in vitro and in vivo experiments show that ALDOA is associated with the proliferation and metastasis of pancreatic cancer cells." (PMID 36968582, 2023). "The relevance between ALDOA and E-cadherin was discovered in pancreatic cancer." (PMID 36030248, 2022). "Our previous study indicated that ALDOA promoted the proliferation and metastasis of pancreatic cancer, partially through the regulation of E-cadherin expression, and predicted a dismal prognosis in patients with pancreatic cancer." (PMID 34565365, 2021). "Furthermore, we transfected the PCMV-PLK1-FLAG plasmid into pancreatic cancer cells with stably silenced ALDOA." (PMID 34565365, 2021). "To explore the effects of ALDOA on the occurrence and development of pancreatic tumours, we analysed the RNA sequencing results and found that ALDOA could inhibit the DDR." (PMID 34565365, 2021). "In pancreatic cancer, HNF4α deletion led to a glycolytic energy metabolism transition from typical pancreatic adenocarcinoma to squamous pancreatic cancer, in which Fructose-Bisphosphate Aldolase A (ALDOA), Hexokinase 1 (HK), and Glycogen Synthase Kinase 3 Beta (GSK3β) genes are upregulated." (PMID 36249028, 2022). "Inhibitors of Class-I aldolases have been used to target cancer cells; the muscle isoform of aldolase (ALDOA) is the most abundant isoform in multiple human cancer types, and its overexpression predicts poor survival probabilities in patients with lung and pancreatic cancer." (PMID 34458323, 2021).
pancreatic cancer (continued). "The HIF1α inhibitor TX-2098 similarly reduced expression of ALDOA and vascular endothelial growth factor (VEGF) in a xenograft model of pancreatic cancer." (PMID 34458323, 2021). "Further studies revealed that ALDOA expression positively correlates with PLK1 expression and negatively correlates with ATM expression in pancreatic cancer patients." (PMID 34565365, 2021). "Both PLK1 and ATM regulate the cell cycle, and it is important to determine whether ALDOA, which connects ATM to PLK1, regulates the cell cycle arrest caused by DNA damage and whether this regulatory mechanism is significant in the development of pancreatic cancer." (PMID 34565365, 2021). "To verify the state of expression of ALDOA, ATM and PLK1 in patient tissues, we randomly selected 78 patients diagnosed with pancreatic cancer in our centre." (PMID 34565365, 2021). "Furthermore, ALDOA could predict poor prognosis in patients with pancreatic tumours." (PMID 34565365, 2021). "Furthermore, five genes (KRT19, ALDOA, CLDN4, RAB27B, and GJB5) among the top 10 % coregulated genes were identified to have significantly elevated expression in pancreatic cancer compared to the normal pancreas." (PMID 40680814, 2025). "ALDOA and PAF1 have recently been described as oncogenes in PDAC, whereas ENO1, RALGDS, TRIP10, and FLNA are known to mediate pancreatic cancer cell proliferation, survival and migration." (PMID 32029502, 2020). "Therefore, the results suggested that PGK1, ALDOA, and LDHA may play important synergistic roles for P4HA1 in pancreatic cancer." (PMID 33415167, 2020).
colorectal cancer (18 papers, 2014 to 2025). A primary or metastatic malignant neoplasm that affects the colon or rectum. "The current study aimed to investigate the role of ALDOA in the initiation and development of colorectal cancer (CRC)." (PMID 39755705, 2025). "They validated their findings through univariate and multivariate analyses of microarray data from 222 resected colorectal cancer samples and revealed that ALDOA was an independent prognostic factor." (PMID 37961749, 2024). "A recent study has revealed that up-regulated ALDOA expression promotes the proliferation, sphere formation, and radio-resistance of colorectal cancer cells." (PMID 34997215, 2022). "Many studies about the dysregulation of the ALDOA gene have emerged in recent years, including colorectal cancer, gastric cancer, and renal cell carcinoma." (PMID 34925439, 2021). "ALDOA has been identified as a marker of late-stage colorectal cancer and lung squamous cell carcinoma, and is involved in osteosarcoma metastasis." (PMID 27128972, 2016). "Overexpression of ALDOA has been observed in a variety of cancers including renal clear cell carcinoma 37, lung squamous cell carcinoma 38, colorectal cancer 39, osteosarcoma 40, and oral squamous cells 41, suggesting that glycolysis is enhanced in these cancer cells." (PMID 33994862, 2021). "Moreover, ALDOA was lately reported as a prognostic marker of colorectal cancer progression, highly expressed in disease stages I and IV." (PMID 24993527, 2014). "However, few study was performed to investigate the relationship between ALDOA and AKT in colorectal cancer." (PMID 38499636, 2024).
osteosarcoma (17 papers, 2014 to 2025). A usually aggressive malignant bone-forming mesenchymal neoplasm, predominantly affecting adolescents and young adults. "The lncRNA KCNQ1OT1 competitively binds to miR-34c-5p to indirectly upregulate ALDOA and facilitates aerobic glycolysis, promoting osteosarcoma proliferation." (PMID 35927226, 2022). "lncRNA KCNQ1OT1 sponges miR-34c-5p to enhances osteosarcoma progression by ALDOA-enhanced aerobic glycolysis." (PMID 35342412, 2022). "ALDOA and ALDOB have been associated with poor prognosis of osteosarcoma and hepatocarcinoma, respectively." (PMID 24959248, 2014).